MUC15 (mucin 15, cell surface associated)
Diseases named in the same sentence as MUC15 in open-access papers (continued):
Sharing a sentence is not in itself a finding about the gene and the disease.
tumor (continued). "No change in MUC15 expression was observed between primary tumours (stage III and IV) and associated metastatic sites (0.96-fold change; P = 0.1294)." (PMID 39483899, 2024). "MUC15 has garnered increasing attention in the realm of tumor development." (PMID 38021164, 2023). "Analysis of patient cohort, patient-derived tumor organoids and patient-derived xenografts further suggests that the MUC15 may predict lenvatinib benefits in HCC patients." (PMID 35236826, 2022). "However, hepatocyte-specific deletion of MUC15 dramatically increased the tumor numbers, maximal tumor sizes and liver-to-body weight ratios." (PMID 35236826, 2022). "Furthermore, the tumor load was markedly reduced by MUC15 overexpression, as indicated by a significant decline in tumor incidence, numbers, maximal tumor sizes and liver-to-body weight ratios in MUC15-TG mice compared with control mice." (PMID 35236826, 2022). "Muc15 is a highly glycosylated extracellular mucin protein previously reported to be expressed in normal epithelial cells, including the breast, but elevated in tumor cell populations." (PMID 25380620, 2014). "However, the role of MUC15 in tumor progression and metastasis is unclear." (PMID 30420637, 2018). "In tumor cells isolated from primary HCC tissues, pearson correlation analysis revealed that MUC15 levels were negatively correlated with the expression of CD24 and EpCAM." (PMID 35236826, 2022). "In contrast, three membrane‐bound MUCINs (MUC1, MUC13, and MUC15), one atypical MUCIN (EMCN), and one secretion MUCIN (MUC6) were significantly downregulated in the tumor samples (p < 0.05)." (PMID 34327857, 2021). "When it comes to MUC15, statistically significant decrease in expression of this mucin was noted in most of the HCC patients, compared to adjacent non-tumour tissue." (PMID 30875782, 2019). "Furthermore, another two hypomethylated genes, MUC15 and HRG, exhibited downregulated mRNA levels in the tumor group." (PMID 35126463, 2021). "Knockdown of MUC15 in HOS and U-2OS could promote tumor cell apoptosis, down-regulate the expression of MMP2/9, reduce the epithelial interstitial transition and silence the Wnt/b-Catenin signal pathway." (PMID 33391443, 2021). "Mucins may act as oncogenes and tumour-promoting (e.g., MUC1, MUC13), and/or tumour-suppressing factors (e.g., MUC15)." (PMID 30875782, 2019). "Importantly, tumors from MUC15‐overexpressing cells showed decreased YAP nuclear localization and reduced α‐SMA expression, indicating that MUC15 regulates both direct metastasis and microenvironment remodeling through tumor cell‐PSC interactions." (PMID 41082352, 2025). "Similarly, manipulating cells by overexpressing MUC15 in MiaPaca‐2 cells inhibited both integrin‐mediated focal adhesion assembly and the ECM remodeling in vivo by tumor cell‐activated PSCs, resulting in suppressed tumor metastasis and progression." (PMID 41082352, 2025). "Moreover, the interference of MUC15 induced hepatocyte transformation in vitro and resulted in tumor formation in a murine subcutaneous tumor model while the control cells did not." (PMID 35236826, 2022). "For tumor cell proliferation, we did not observe any significant changes in MUC15 knocking-down ACHN or Caki-1 cells, and MUC15 overexpressed 786-O cells." (PMID 32382053, 2020). "In addition, lowered expression of MUC15 was significantly correlated with the TNM stage, intrahepatic or lymphatic metastasis, portal vein thrombosis, high levels of AFP, vascular invasion, lack of encapsulation and poor tumour differentiation." (PMID 30875782, 2019).
infection (6 papers, 2011 to 2020). The state of being infected such as from the introduction of a foreign agent such as serum, vaccine, antigenic substance or organism. "BALB/c mice were infected with HMPV, and the expression of Muc1, Muc2, Muc4, Muc5ac, Muc5b, Muc15, Muc16, Muc19, and Muc20 were analyzed at 12, 24 and 48 h after infection." (PMID 32899224, 2020). "We found that the expression of MUC15 was significantly upregulated upon infection, and specific only to active infection." (PMID 31307416, 2019). "Taken together, these findings suggested an interaction between MUC15 and immunomodulatory factors late into infection with H3N2 virus, and warrants further investigation to establish their exact immunomodulatory mechanisms." (PMID 31307416, 2019). "However, we observed decreased levels of EGFR, ERK and pERK in the late phase of infection, which coincided with strong induction of MUC15 in the nasal epithelium, indicating its potential role in immune-modulation, possibly via other indirect means." (PMID 31307416, 2019). "Given that the upregulation of MUC15 was only triggered late into infection when immune factors (including cytokines, chemokines, EGFR and phosphorylated ERK) started to peak and plateau, MUC15 may potentially serve an immunomodulatory function later during influenza viral infection." (PMID 31307416, 2019). "Another interesting finding was that the upregulation of MUC15 expression only occurred during active infection of the nasal epithelial cells, rather than by UV-inactivated virus or viral mimics like poly (I:C)." (PMID 31307416, 2019). "Attempts at siRNA transfection on hNECs yielded MUC15 knockdown in the absence of infection, but was weaker during infection due to the high levels of MUC15 expression and activation, albeit the increase of IFNβ and CXCL10 was observed." (PMID 31307416, 2019). "Our data indicate that the MUC expression by RSV and hMPV differs significantly, as we observed a stronger induction of MUC8, MUC15, MUC20, MUC21, and MUC22 by RSV infection while the expression of MUC1, MUC2, and MUC5B was dominated by the infection with hMPV." (PMID 25977598, 2015). "No major changes were observed in Muc1, Muc15 and Muc20 levels during chronic or acute infection when compared to uninfected control mice (day 21 pi." (PMID 21155842, 2011). "Hpi: hours post infection; NT: non-targeting control; M15: MUC15 siRNA." (PMID 31307416, 2019). "Compared to uninfected cells, HMPV infection induced a significant fold-increase expression of MUC1 (8.3 ± 2), MUC2 (43.4 ± 13), MUC4 (54 ± 12), MUC5ac (23.3 ± 11.5) and MUC19 (77 ± 35), while no significant induction of MUC15, MUC16 and MUC20 was observed." (PMID 32899224, 2020).
MUC15 also shares sentences with these, for which no sentence is quoted: squamous cell carcinoma (2 papers); stomach adenocarcinoma (2); basal cell carcinoma (1); colon adenocarcinoma (1); colorectal adenocarcinoma (1); colorectal tumors (1); esophageal squamous cell carcinoma (1); follicular thyroid cancer (1); laryngeal carcinoma (1); lung adenocarcinoma (1); metastatic melanoma (1); mucinous colorectal adenocarcinoma (1); neuroblastoma (1); pancreatic adenocarcinoma (1); papillary thyroid carcinoma (1); preeclampsia (1); type 1 diabetes (1).